HIF1A (hypoxia inducible factor 1 subunit alpha)
Diseases named in the same sentence as HIF1A in open-access papers (continued):
Sharing a sentence is not in itself a finding about the gene and the disease.
diabetes (continued). "To examine whether AKR1C downstream pathways are possibly also altered in diabetes, we investigated further genes involved in oncogenic processes such as proliferation and HIF1α and NFκB pathways." (PMID 32932589, 2020). "However, animal study suggests that HIF-1α still regulates IL-6 expression in diabetic retina as increased HIF-1α, IL-6, and TNF-α are found in diabetic retina of diabetic rats, which can be decreased by the HIF-1α inhibitor." (PMID 33013692, 2020). "Accordingly, it is speculated that HIF-1α may be involved in the process of inflammation, angiogenesis, and vascular endothelial injury in diabetes." (PMID 33456489, 2020). "Moreover, HIF-1α is a critical element in the hypoxia environment, both diabetes and tumor vessels, to modulate angiogenesis and hypoxia response." (PMID 32680978, 2020). "Notably, a reduced percentage of PIL expressed granzyme B when RIP-gp mice were given HIF-1α-Tg BMDCs, coinciding with the limited induction of islet cell death and reduced frequency of diabetes induction in the RIP-gp model." (PMID 33382742, 2020). "Expression of HIF1a was significantly higher in the diabetes CD14 monocytes (p < 0.05)." (PMID 32210958, 2020). "In addition, we found that luseogliflozin decreased diabetes-induced HIF-1α expression in proximal tubular cells and tubulointerstitial injury in the renal cortex in db/db mice." (PMID 31611596, 2019). "In summary, these results highlight the role of proteasome-dependent mechanisms of HIF-1α degradation on diabetes-induced HK-2 cells dysfunction and suggest that cell-derived microparticles may mediate negative effects of the diabetic milieu on PTC." (PMID 31676796, 2019). "We found decreased Cd36 mRNA in the diabetes-exposed Hif1a+/− offspring compared to other groups." (PMID 29753320, 2018). "We questioned whether abnormal FA metabolism could drive abnormal HIF-1α activation and downstream adaptation to hypoxia in diabetes." (PMID 30175272, 2018). "Although increased cardiac fibrosis is a hallmark of structural remodelling in response to a diabetic environment, we paradoxically found decreased collagen deposition along with decreased expression of Tgfb1 in both Hif1a+/− and Wt diabetes-exposed LV at 12 weeks of age." (PMID 29753320, 2018). "Both diabetes-exposed Wt and Hif1a+/− males had a lower heart rate at 12 weeks of age, which may indicate changes in cardiovascular autonomic regulation." (PMID 29753320, 2018). "We focused on differentially expressed genes showing ≥ 30% change in any of the groups compared to Wt from non-diabetic pregnancy, representing 144 differentially expressed genes; the majority of changes (95 genes) were identified only in the diabetes-exposed Hif1a+/− hearts." (PMID 29753320, 2018). "However, the compromised function of HIF-1α in diabetes, which is induced by high glucose and reactive oxygen species (ROS), leads to impaired HIF-1α transactivation and reduced neovascularization." (PMID 30338719, 2018). "Thus, our data provide evidence of differential regulation of Vegfa in cardiac tissue and coronary macrovasculature of the diabetes-exposed Hif1a+/−." (PMID 29753320, 2018). "Interestingly, the heart of diabetes-exposed Hif1a+/− offspring had a globular shape with less elongated and more globular ventricles compared to the hearts in others groups of adult offspring." (PMID 29753320, 2018). "Echocardiographic analyses of the LV function in 1- and 12-week-old offspring disclosed a significant decrease in fractional shortening (FS) in diabetes-exposed Hif1a+/− compared to diabetes-exposed Wt (P < 0.001), and unexposed Wt or Hif1a+/− controls (P < 0.0001) at 12 weeks of age." (PMID 29753320, 2018). "Elevated serum HIF-1α may be involved in vascular calcification in patients with type 2 diabetes mellitus." (PMID 29296174, 2017). "Significant interaction effect of diabetes with DOX was observed in HIF-1α (P = 0.05)." (PMID 27512375, 2016).
diabetes (continued). "However, under STZ-induced diabetes, Hif1a+/- mice exhibited faster deterioration of cardiac functional parameters associated with diabetic cardiomyopathy compared to diabetic Wt mice." (PMID 24502509, 2014). "Furthermore, the mRNA and protein expression levels of HIF-1α in the severe diabetes group were significantly upregulated compared with the other groups." (PMID 25371752, 2014). "In addition, the western blot analysis results demonstrated that the protein expression levels of HIF-1α in the severe diabetes group were significantly elevated compared with the control (P<0.01) and mild diabetes groups (P<0.05)." (PMID 25371752, 2014). "However, when the severity of cerebral injury induced by diabetes reaches a certain level, HIF-1α enters the blood circulation from the brain." (PMID 25371752, 2014). "Furthermore, the protein expression of HIF-1α in the mild diabetes group was significantly higher compared with the control group (P<0.05)." (PMID 25371752, 2014). "Previous studies have clarified the relationship between HIF-1α and diabetes." (PMID 24564828, 2014). "However, based on our VEGF-A expression data, the HIF-1a functional activity is affected by the combination of Hif1a haploinsufficiency and diabetes." (PMID 24502509, 2014). "However, the harmful effects of diabetes were clearly more pronounced in Hif1a+/- mice as illustrated by the significantly decreased FS." (PMID 24502509, 2014). "According to multivariate logic analyses, after adjustment for cardiovascular risk factors such as age, gender, SBP, BMI, smoking, diabetes duration, HbA1c, CRP, IL-6, LDL and medication, HIF-1α levels still significantly and independently predicted the presence of CAC." (PMID 24564828, 2014). "In the present study, the mRNA and protein expression levels of HIF-1α in patients with severe diabetes were significantly higher compared with those in the other two groups, indicating that local hypoxia may exist in the brains of severely diabetic patients." (PMID 25371752, 2014). "Thus, it is possible that treatments that enhance myocardial HIF-1α/HO-1 expression in response to ischemia reperfusion under hyperglycemic conditions should confer cardioprotection in diabetes." (PMID 23874823, 2013). "Taken in conjunction, the findings by others and the present results suggest that the HIF-1 α/HO-1 pathway plays an essential role in cardioprotection against MI/R injury in diabetes, although the detailed regulation of the involvement of HIF-1α/HO-1 signaling warrants further investigation." (PMID 23874823, 2013). "Thus, the present findings indicate that the cardioprotective effects in diabetes resulting from the combination of NAC plus ALP were achieved primarily through the restoration of HIF-1α/HO-1 signaling in response to MI/R." (PMID 23874823, 2013). "Since VEGF is considered a survival factor for tubular cells, our findings suggest that diabetes displays HIF-1α upregulation that might function as a “precondition state” offering protection from endotoxic AKI." (PMID 23984430, 2013). "Therefore, for patients with both diabetes and cancer, combination therapy strategies that target HIF-1α alongside traditional cancer treatments and diabetes management might be particularly beneficial." (PMID 39996906, 2025). "Therefore, we speculate that Pue may inhibit ceramide production through the HIF-1α pathway, thus improving the pathological process of diabetes and providing a novel direction for studying how Pue functions in diabetes treatment." (PMID 40143173, 2025). "Therefore, an in-depth study of the mechanisms of how Pue affects HIF-1α may reveal new therapeutic targets and provide new strategies for the treatment of diabetes and its complications." (PMID 40143173, 2025). "Notably, metabolic disturbances in diabetes can induce tissue hypoxia, and subsequent activation of HIF-1α may contribute to testicular dysfunction." (PMID 40867634, 2025).
diabetes (continued). "Thus, the model here with reduced β-cell HIF1α is of relevance to diabetes." (PMID 39769216, 2024). "Similarly, the number of neurons expressing NeuN, a marker of mature neurons, exhibited a decrease in both maternal diabetes and Hif1a mutation conditions, with no observed additive combinatorial effect of Hif1a mutation within the diabetic environment." (PMID 38505753, 2024). "Therefore, we further investigated whether SF-DFO can alleviate diabetes symptoms in aged 72-week-old mice by restoring the HIF-1α-RegIIIγ pathway in osteoblasts." (PMID 38945950, 2024). "Therefore, in diabetes, there is often impaired HIF-1α signaling." (PMID 39769216, 2024). "In addition to increasing bone mass and reducing blood glucose levels, this study revealed that activating the HIF-1α pathway by specifically knocking out Vhl in osteoblasts partially alleviated the symptoms of streptozotocin (STZ)-induced type 1 diabetes mellitus (T1DM)." (PMID 38945950, 2024). "However, NOD mice with deleted HIF-1α in their β-cells had 100% diabetes incidence after MLDS." (PMID 39769216, 2024). "Following our identification of protective effects of β-cell HIF-1α in islet transplantation and in resistance to diabetes following viral exposure, we tested whether β-cell HIF-1α is important for preventing β-cell death and diabetes after exposure to the β-cell toxin streptozotocin (STZ)." (PMID 39769216, 2024). "Conversely, a recent study suggests that enhanced glucose uptake or during Diabetes Mellitus in TB patients (TB-DM), the increased glucose levels negatively regulate HIF-1α, and thus mediates the survival of M.tb in the infected macrophages." (PMID 38312835, 2024). "Finally, although no available data has yet been reported on the role of HIF-1α, it could be speculated that a ROS-HIF-1α-autophagy cascade plays a role in autophagy (mitophagy)-mediated β cell dysfunction and diabetes pathogenesis." (PMID 37189396, 2023). "Furthermore, there is evidence that the two main members of the HIF family (i.e., HIF-1α and HIF-2α) have different effects on redox balance, inflammation, and fibrosis, which are the major pathogenic mechanisms of tissue damage associated with diabetes." (PMID 36358555, 2022). "Therefore, strategies aimed at modulating HIF-1α signaling may be promising new treatments for diabetes and its complications." (PMID 35684364, 2022). "Moreover, HIF-1α is not only involved in OSA, but it is also linked to IR and diabetes." (PMID 34209501, 2021). "Moreover, we decided to analyze diabetes-evoked differences in the cellular response to high glucose, determining HIF-1α expression in primary cells: D-RPTEC (Diseased Human Renal Proximal Tubule Epithelial Cells—Diabetes Type II) and RPTEC (Renal Proximal Tubule Epithelial Cells)." (PMID 34948094, 2021). "Results from a recent study revealed that the miR-1248/CITED2/HIF-1α axis played a significant role in diabetic wound healing, indicating that miR-1248 may be used as a novel therapeutic target for wound healing in patients with diabetes." (PMID 32634115, 2020). "In summary, we found that stem cell proliferation activity and angiogenesis of hADSCs under diabetes-associated glucolipotoxic conditions were increased in part by modulating the expression of miR-1248 via restraining the expression of CITED2, an inhibitor of HIF-1α." (PMID 32294623, 2020). "Taken together, HIF-1α, MK2 and PTEN expression all correlated with the morphometric index of vascular integrity, i.e. capillary luminal area or capillary basement membrane thickness, indicating that the activation of these molecules was associated with diabetes-induced microvascular insults." (PMID 29549140, 2018). "Although diabetes might have a complex repressive effect on the stabilization and transactivation of HIF-1α, our results indicated that HIF-1α expression was associated with better nerve profiles." (PMID 29549140, 2018).
diabetes (continued). "This diabetes-mediated decrease in HIF-1α protein expression could stem from a defect in phosphorylated Akt (pAkt)-mTOR-dependent signaling because this pathway has been shown to stimulate HIF-1 translation in response to nutrient, growth factors and forskolin." (PMID 25381014, 2015). "However, diabetes significantly influenced the LV echocardiographic parameters of Hif1a+/- mice." (PMID 24502509, 2014). "Therefore, the effects of HIF-1α on the progression of diabetes remain controversial." (PMID 24705496, 2014). "The novel finding that NAC and ALP attenuate high glucose-induced MPTP opening in cardiomyocytes during hypoxia/re-oxygenation via HIF-1α/HO-1 signaling may have potential clinical importance in guiding the development of effective therapies to combat myocardial ischemia in diabetes." (PMID 23874823, 2013). "Key angiogenic drivers in the diabetic retina include vascular endothelial growth factor (VEGF), insulin/insulin-like growth factors (IGF), and hypoxia-inducible factor-1 alpha (HIF-1α), which are upregulated in response to hyperglycemia and retinal ischemia." (PMID 41010004, 2025). "In diabetes, however, reduced levels of IGF-1 and TGF-β impair fibroblast and keratinocyte recruitment, hyperglycaemia destabilizes HIF-1α and suppresses VEGF expression, macrophages are dysfunctional, and MMP/TIMP imbalance degrades ECM." (PMID 41614737, 2025). "In this study, through bioinformatics analysis, we screened seven DCRGs, including PPARG, MMP9, CTNNB1, TNF, TGFB1, PTGS2, and HIF1A, and established a DCIN to comprehensively understand the diabetes-inflammation-cancer interaction." (PMID 37033970, 2023). "More interesting, combined with diabetic condition, the expressions of HIF-1α, ANG1 and VEGF were all significantly decreased in spinal cord, suggesting that diabetes seriously blocks the angiogenesis in spinal cord after SCI." (PMID 37215981, 2023). "Warburg effect, HIF-1α, and PKM2 in diabetes: team members or individual runners on the road to complications?" (PMID 37305566, 2023). "Serum levels of miR-217, HIF-1α, and VEGF were measured in patients with DFU, in patients with simple diabetes mellitus (DM), and in healthy controls." (PMID 37664860, 2023). "Collectively, balancing HIF-1α and promoting HIF-2α activity offers promising prospects in addressing cardiovascular diseases and conditions like diabetes and chronic kidney disease." (PMID 37981648, 2023). "Three months after the induction of diabetes, the DM rats showed changes indicative of retinopathy such as decrease in the thickness of retina, increase in the expression of VEGF and HIF-1α and decrease in the expression of rhodopsin." (PMID 35439275, 2022). "Paradoxically, hyperglycemia also activates HIF-1α signaling in glomerular mesangial cells, suggesting that HIF-1α regulation is context-specific in diabetes." (PMID 35684364, 2022). "Particularly, HIF-1α and its effector Pfkfb3 were activated in islets from individuals with T1DM and streptozotocin-induced diabetes mouse liver." (PMID 35955706, 2022). "HIF-1α inhibitors can be widely used in the treatment of various diseases related to HIF-1 overexpression, such as tumors; leukemia; diabetes and its complications; ischemic, cardiovascular and brain diseases; and inflammatory diseases, etc." (PMID 35684364, 2022). "Here, the authors design a small molecule that stabilizes HIF1α by blocking its interaction with VHL and show that it promotes wound healing in mouse models of diabetes." (PMID 34099651, 2021). "In a different study, β-elemene exerted retino-protective effect by downregulation of hypoxia-inducible factor–1alpha (HIF-1α), VEGF, iNOS, and pro-inflammatory mediators during diabetes progression in a streptozotocin (STZ)-induced rat model." (PMID 32235333, 2020). "In vivo, glucocorticoids injected into murine eyes decreased diabetes‐induced retinal galectin‐1 and TSC22D3 expression and HIF‐1α protein up‐regulation." (PMID 32150332, 2020).
diabetes (continued). "Hence, the increased transcriptional activity of HIF-1α but not stability may provide a functional explanation for the protective effect of HIF1A Pro582Ser mutation on the risk of diabetes and diabetic complications." (PMID 32658866, 2020). "We next asked whether HIF-1α could be mediating the production of immunosuppressive factors or limiting pro-inflammatory cytokine production that could potentially explain the reduced diabetes incidence observed with HIF-1α-Tg BMDC vaccination in the RIP-gp model." (PMID 33382742, 2020). "Since the prostate tissue of patients with T2D AKR1C1, C2, and C3 transcripts showed positive associations with proliferative, HIF1α, and NFκB genes, our results suggest that in the prostate gland, AKR1C enzymes could be involved in the induction of inflammatory processes induced by diabetes." (PMID 32932589, 2020). "Western blotting showed high levels of HIF‐1α, SP1 and ROBO4 after 4 weeks of uncontrolled diabetes, with levels sustained at 6 and 8 weeks." (PMID 31094072, 2019). "Nephroseq analysis revealed increased expression of HIF1α, ZEB2, and TRPC6 in Nakagawa CKD dataset and Hodgin Diabetes Mouse Glomeruli datasets." (PMID 31784544, 2019). "Pathways linked to immunometabolism were of particular interest, including type 1 and type 2 diabetes mellitus signaling, PPARα/RXRα activation, cyclic AMP (cAMP)-mediated signaling, and HIF1α signaling." (PMID 31825836, 2019). "To elucidate the mechanism of SWJH inhibiting renal fibrosis, we examined the effects of SWJH on the expression of HIF-1α, TGF-β1, and VEGF in diabetic kidneys using real-time PCR." (PMID 30420600, 2018). "In contrast, the 12wMP rats exhibited high levels of HIF-1α and VEGF protein, which protected the sciatic nerves against diabetes-induced degeneration." (PMID 27057201, 2016). "The expression of HIF-1α was 5.48±0.51 in the STZ-induced diabetes group, 1.64±0.38 in the STZ-induced diabetes and 250 mg/kg betaine-treated group and 1.11±0.10 in the STZ-induced diabetes and 500 mg/kg betaine-treated group." (PMID 25891515, 2015). "Intriguingly, however, CREB-DNA binding and CRE transcriptional activity essential parameters for HIF-1α and VEGF formation were diminished during the course of diabetes." (PMID 25381014, 2015). "As an attempt to illustrate the molecular mechanism of the diabetes-related decrease in VEGF expression and its implications for impaired angiogenesis, we examined the PKA-CREB and HIF-1α dynamics in diabetic SIECs." (PMID 25381014, 2015). "Our results are indirectly supported by a study showing that the overexpression of Hif1a gene under the control of the myosin heavy chain promoter normalizes VEGF-A levels and inhibits fibrosis in hearts exposed to diabetes." (PMID 24502509, 2014). "In the in vivo study employing db/db mice treated with 10 mg/kg PCE for 8 weeks, PCE alleviated glomerular angiogenesis of diabetic kidneys by attenuating the induction of VEGF and HIF-1α." (PMID 24278186, 2013). "It has been shown that diabetes impairs HIF-1α and VEGF expressions, as well as low levels of HIF-1α expression in foot ulcer biopsies in patients with diabetes, have been evidenced." (PMID 23197976, 2012). "Diminished production of HIF-1α and its target genes such as VEGF are thought to contribute to insufficient angiogenesis that results in impaired tissue repair in diabetes." (PMID 22125629, 2011). "Future research should prioritize the development of personalized treatment algorithms based on individual molecular biomarker profiles, particularly HIF-1α, inflammatory markers, and adipokine patterns, to optimize therapeutic selection for patients with OSA and diabetes." (PMID 41155523, 2025). "HIF-1α is not responsive in diabetics, as hyperglycemia impairs the HIF-1a transactivation, resulting in decreased hypoxia-induced VEGF expression." (PMID 40149539, 2025).